BCHE (butyrylcholinesterase)
Diseases named in the same sentence as BCHE in open-access papers (continued):
Sharing a sentence is not in itself a finding about the gene and the disease.
liver disease (14 papers, 2011 to 2025). "Abnormal serum levels of cholinesterase (ChoE, also butyrylcholinesterase or pseudocholinesterase), a hydrolytic enzyme synthesized in the liver, have been associated with different pathologies, including malnutrition, non-liver diseases, chronic inflammation, and cancer." (PMID 37294372, 2023). "Thus, the association of low BChE with higher CV mortality may result from a pre-existing liver disease—as metabolic liver damage and/or NASH share similar risk factors as ACS—that may modulate the course ACS and ultimately cardiac mortality." (PMID 25933219, 2015). "BChE levels are low in systemic conditions like liver disease, renal disease, malnutrition, malignancies, and burns." (PMID 40870535, 2025). "Butyrylcholinesterase (BChE) is produced in the liver and its serum levels have been shown to be prognostic markers of liver disease." (PMID 39554341, 2024). "This reduced level of BChE in serum indicates many clinical conditions of the liver disorder, including infection, inflammation, injury, and both acute and chronic liver damage." (PMID 39554341, 2024). "BChE is used as a marker to predict the prognosis of several disorders (inflammatory diseases, infection, malnutrition, malignancy, critical illness, liver disease, and metabolic diseases), but the role of BChE in HIV/AIDS is incompletely understood." (PMID 29736152, 2018). "The possibility to monitor changes not only in serum BChE activity, but also in the soluble AChE-R, as a function of liver disease progression and prognosis requires further consideration." (PMID 23028565, 2012). "The absolute levels of AAA were increased as BChE activity decreased while deviating from normal samples and such deviation was directly proportional to the severity of the liver disorder." (PMID 21989042, 2011). "It must thus be borne in mind that altered expressions or activities of BChE could be impacted not only by genetic facets but also by diseases and unhealthy conditions, such as CNS disorders, liver disease, inflammation, and smoking." (PMID 39766923, 2024). "Additionally, a decrease in plasma BChE activity was observed in hepatic diseases." (PMID 29780825, 2018). "First of all, we evaluated a possible relationship between baseline serum BChE activity levels and subsequent severe transplant-related liver disorders (SOS and third-grade liver disease)." (PMID 31185690, 2019). "BChE activity is known to be a marker of impaired liver synthesis, meaning that other non-cancer related pre-existing liver diseases might influence the activity and contribute as co-morbidities and confounders to the prognostic significance of the marker." (PMID 32375339, 2020).
malnutrition (14 papers, 2014 to 2026). Inadequate nutrition resulting from poor diet, malabsorption, or abnormal nutrient distribution. "BChE and Nutritional Status - BChE is used as a potential biomarker for evaluating nutritional status, especially in persons suffering from malnutrition or protein deficiencies." (PMID 40612057, 2025). "Since BChE has been associated with malnutrition, chronic inflammation, and impaired liver function, as well as advanced tumor stage, it is a promising prognostic tool to consider during decision-making for treatment regimes in oncologic patients." (PMID 37280384, 2023). "Deficiency in butyrylcholinesterase (BChE), a condition commonly noticed in liver damage, inflammation, and malnutrition, has previously been associated with impaired prognosis in different malignancies." (PMID 30737542, 2019). "Among these, butyrylcholinesterase—a liver-synthesized enzyme that decreases in states of systemic inflammation and malnutrition—has emerged as a potential biomarker reflecting the systemic host response." (PMID 41597477, 2026). "Decreased serum BChE was observed in patients with chronic inflammation, malnutrition, and malignant disease, serving for instance as a potential biomarker for organ damage and impaired liver function." (PMID 37280384, 2023). "Thereby, rather an inadequate availability of substrates for its synthesis as opposed to hepatocellular failure seems to be responsible for a decrease in BChE during malnutrition." (PMID 30737542, 2019). "First, malnutrition and wasting syndrome are associated with protein-energy malnutrition (PEM) and accounted for a reduction in the serum level of BChE." (PMID 29736152, 2018). "In summary, BChE and albumin levels should be interpreted in the context of systemic inflammation and malnutrition, both conditions that are hallmarks of malignant disease." (PMID 29113384, 2017). "Low BChE serum levels have been reported in many clinical conditions such as liver damage, inflammation, injury, and malnutrition." (PMID 24741368, 2014). "In geriatric patients, BChE levels have been suggested as a useful biomarker for malnutrition or a disease prognostic indicator." (PMID 24741368, 2014). "BChE levels declined in acute and chronic liver damage, cirrhosis, hepatocellular carcinoma and protein–energy malnutrition, being a biomarker for liver impairment and malnutrition." (PMID 41186080, 2025). "Patients on dialysis with low serum BChE levels often present with low albumin levels which may be overlooked as malnutrition." (PMID 38420074, 2024). "Moreover, decreased serum BChE levels have been observed in various clinical conditions, such as stress, chronic inflammation, and malnutrition." (PMID 30737542, 2019). "Furthermore, reductions in serum BChE can be found in various clinical conditions, such as injury, liver damage, infectious disease, and malnutrition." (PMID 30737542, 2019). "Since an association of decreased serum BChE levels and malnutrition independent of cancer disease was described previously, further evaluation of chronic inflammation, malnutrition, and the association of serum BChE levels in tumor patients would be of interest." (PMID 37280384, 2023). "However, in ccRCC patients, low serum BChE levels could suggest other systemic disorders, including poor PS or secondary malnutrition." (PMID 24741368, 2014).
depression (13 papers, 2010 to 2025). "Future research, including BChE measurements, may help clarify its relevance in the association between hepatic steatosis and depression." (PMID 41011102, 2025). "An important physiological role of BCHE gene (degree > 20) is to reduce the background levels of ghrelin in the brain to control anxiety and depression." (PMID 38257381, 2024). "Less duration in central is the primary index of anxiety or depression, and the BChE inhibition groups showed the same duration in central compared to the WT group, indicating that BChE inhibition did not affect the anxiety level." (PMID 34062954, 2021). "Median and interquantile range (IQR) of neurological symptoms and signs of the two cohorts according to BChE activity (in each cohort, depression in BChE activity was determined relative to normal ranges from the methods used)." (PMID 28231336, 2017). "Finally, docking studies suggest potential future applications of the MTDL 3c in complex diseases such as major depression and AD, which involve targeting AChE and/or BChE enzymes and melatonin MT1 and MT2 receptors." (PMID 37765003, 2023). "Our results indicated that 2t is a potent inhibitor of MAO-A, MAO-B, and BChE enzymes, and could be a promising candidate for preclinical development for the treatment of depression, AD, and PD." (PMID 36838642, 2023). "A forced swimming test was carried out to evaluate the effect of BChE on depression." (PMID 34062954, 2021). "Although early evidence suggests that butyrylcholinesterase is more labile than other forms, it is possible that our cut point for defining cholinesterase depression (15% change) may have resulted in misclassification." (PMID 20085857, 2010). "Our result showed that the immobility time of BChE+/− and BChE−/− mice was significantly lower than that of the wild-type control group, indicating that BChE KO enhanced resistance to despair, BChE inhibition will possibly ameliorate the depression during PTSD treatment." (PMID 34062954, 2021). "The inhibition of BACE1, AChE, and BChE, in AD, hMAO-B in PD, and MAO-A in depression was performed efficiently by SPs, glycoproteins, carotenoids, especially fucoxanthin, and phlorotannins." (PMID 35736165, 2022). "Subsequently, APOD, PON1, BCHE, and IL6ST were reported to be related to depression, a finding consistent with our results." (PMID 33126421, 2020). "Besides, administration of (R)-bambuterol increased the spatial learning and memory ability in the water-maze test, which were utterly consistent with the results in BChE KO mice, suggesting the potential of bambuterol in the treatment of PSTD, depression and neurodegenerative diseases." (PMID 34062954, 2021). "While the relationship between neurological symptoms and BChE depression is obvious, this is not the case regarding neurobehavioral performance, where only one test (Trail Making) showed a negative correlation with BChE levels in the 2005 cohort." (PMID 28231336, 2017). "In addition, participants with depressed BChE activity showed more symptoms and signs than others without BChE depression (p < 0.05)." (PMID 28231336, 2017).
delirium (12 papers, 2015 to 2025). A disorder characterized by confusion; inattentiveness; disorientation; illusions; hallucinations; agitation; and in some instances autonomic nervous system overactivity. "Increased and decreased levels of AChE activity have been associated with an increased risk of postoperative delirium (POD) and delirium during critical illness, while decreased levels of BChE have been associated with increased inflammatory processes and also an increased risk of POD." (PMID 39715945, 2024). "This study aimed to investigate the relevance of BChE activity as a biomarker for postoperative delirium after cardiac surgery or percutaneous valve replacement." (PMID 38424490, 2024). "Previous research on AChE and BChE activities has mainly focused on perioperative settings, examining their potential as biomarkers of delirium." (PMID 39715945, 2024). "Due to recent studies which supposed an important role of AChE and BChE in delirium of critically ill patients this study focused on AChE and BChE in patients after cardiac surgery and its impact on postoperative delirium." (PMID 28560042, 2017). "Neither preoperative nor postoperative BChE activity was independently associated with the occurrence of postoperative delirium (p = 0.086, p = 0.484)." (PMID 38424490, 2024). "In the context of POD, emerging evidence suggests that alterations in BChE activity may influence cholinergic dysregulation, contributing to the cognitive disturbances seen in delirium or other dementia-related diseases." (PMID 39713214, 2024). "We tested the hypothesis that AChE and BChE have an impact on patients after cardiac surgery with postoperative delirium." (PMID 28560042, 2017). "In order to increase the understanding of the relationship between the cholinergic and immune systems with regard to delirium pathophysiology, we will also measure biomarkers plasma acetylcholinesterase and butyrylcholinesterase, as indicators of cholinergic function." (PMID 25982544, 2015). "BChE activity is not independently associated with the occurrence of postoperative delirium." (PMID 38424490, 2024). "Thus, our results underpin the thesis, that overexpression of BCHE might aggravate postoperative delirium, due to an increased hydrolysis of acetyl-choline." (PMID 35802656, 2022). "However, lower enrollment BChE activity levels were associated with fewer days alive without delirium or coma over the following 14 days (P = 0.048), indicating worse acute brain dysfunction." (PMID 36474266, 2022). "Additionally, lower BChE activity was associated with fewer days alive without delirium or coma." (PMID 36474266, 2022). "A recent study looking into the BioCog patients concluded that a decrease in BchE activity was noticed more prominently in patients with postoperative delirium and complications, as opposed to uncomplicated patients." (PMID 39229253, 2024). "AChE activities tends to decrease postoperatively in patients with delirium more, but remain stable in patients without delirium, while BChE activities decrease postoperatively in both, patients with and without delirium." (PMID 36894596, 2023). "Recent research found a potentially important role of acetylcholinesterase (AChE) and butyrylcholinesterase (BChE) in delirium of critically ill patients on non-surgical ICU or in non-cardiac-surgery patients." (PMID 28560042, 2017). "Furthermore, compared to other clinical screening tools that can indicate an onset of delirium such as CAM-ICU or NuDesc, our ROC-analysis of preoperative BChE activity showed only low sensitivity and moderate specificity for the predictive evaluation of the development of POD." (PMID 38424490, 2024).
prostate carcinoma (12 papers, 2017 to 2025). A carcinoma that arises from epithelial cells of the prostate gland. "In particular, alterations to the expression of BChE in prostate cancer DU-145 cells have been reported and evidence has been found to support that BChE upregulation is associated with cancer recurrence." (PMID 40430552, 2025). "Besides, a lower level of BCHE in the serum is closely associated with the advanced stage and poor prognosis of various cancers, such as gastric cancer, renal cancer, bladder cancer, prostate cancer, and cervical cancer." (PMID 35236335, 2022). "There is a growing body of literature showing the importance of differential expression of serum BCHE in tumours, such as prostate cancer, pancreatic cancer, and HNSCC." (PMID 36818393, 2023). "In retrospective analyses of clear cell renal carcinoma patients, invasive bladder cancer and prostate cancer, preoperative BChE levels were an independent prognostic factor for overall survival." (PMID 29113384, 2017). "Furthermore, in prostate cancer, BCHE expression decreases in the early stages but increases during advanced stages." (PMID 40751365, 2025). "In prostate cancer, BCHE expression is down-regulated early on and up-regulated in the late stage." (PMID 38357546, 2024). "Moreover, in prostate cancer, BCHE expression was downregulated at early stages and upregulated at advanced stages." (PMID 35915658, 2022). "However, the level of BCHE was found to be an important survival factor for patients with prostate cancer." (PMID 35236335, 2022). "For instance, low BChE level was revealed as an independent marker of shorter survival time in colorectal carcinoma, upper tract urothelial carcinoma, clear cell renal cell carcinoma, prostate cancer and cervical cancer." (PMID 32375339, 2020).
glaucoma (11 papers, 2017 to 2025). Increased pressure in the eyeball due to obstruction of the outflow of aqueous humor. "Cholinesterase (ChE), divided into two enzymes acetylcholinesterase (AChE) and butyrylcholinestarase (BChE), have been identified as potential targets in the treatment of AD, myasthenia gravis and glaucoma." (PMID 35701630, 2022). "The research and design of new inhibitors for the treatment of diseases such as Alzheimer's disease and glaucoma through inhibition of cholinesterases (ChEs; acetylcholinesterase, AChE and butyrylcholinesterase, BChE) and carbonic anhydrase enzymes are among the important targets." (PMID 40129107, 2025). "BChE activity is additionally affected by flavonoids or natural anticholinesterase toxins in food and drugs whose bioconversion involves the action of BChE, like echothiophate, eye drops for glaucoma treatment, anti-Alzheimer drugs or the bronchodilator bambuterol." (PMID 28573890, 2017). "Additionally, we believe that these results may be useful for the synthesis of new hCA I and II isoenzymes, AChE and BChE inhibitors, and in the development of drugs for the treatment of some common and global diseases including edema, epilepsy, glaucoma, mountain sickness, and AD." (PMID 36986640, 2023).
neuroblastoma (11 papers, 2019 to 2025). Neuroblastoma (NB) is the most common solid, extracranial childhood tumor. "For instance, the low surface/extracellular staining of AChE, in contrast to the high BChE staining observed in neuroblastoma cells, challenges the canonical view that AChE is the primary membrane-anchored extracellular enzyme responsible for ACh hydrolysis within synapses." (PMID 41226363, 2025). "In an in-vitro model containing SH-SY5Y neuroblastoma cells, U343 glioblastoma cells, and human peripheral blood mononuclear cells, we found that midazolam altered the activity of acetylcholinesterase /buturylcholinesterase (AChE / BChE)." (PMID 35802656, 2022). "Surface flow cytometric analyses indicated that BChE, α7 AChR, and M1 AChR were present at the cell surface of SH-SY5Y neuroblastoma cells, while only minimal levels of AChE were detected extracellularly or at the cell surface." (PMID 41226363, 2025). "Similarly, surface confocal microscopy analysis validated the presence of AChE, BChE, M1-mAChR, and α7-nAChR on the surface of SH-SY5Y neuroblastoma cells." (PMID 41226363, 2025). "Treatment of the AD SH-SY5Y (human neuroblastoma cells) cell model with DPEO resulted in decreased intracellular levels of Aβ, GSK-3β, P-Tau, IL-1β, TNF-α, IL-6, COX-2, OFR, and HFR, alongside reduced AchE and BchE activities and increased SOD activity." (PMID 39056736, 2024). "Based on the model system of cholinergic differentiation in human-derived neuroblastoma cells, we expected to observe neuronal upregulation of AChE-S and AChE-R but no change in BChE mRNA transcripts." (PMID 36117917, 2022). "Next, the anti-butyrylcholinesterase enzyme (BChE), reactive oxygen species (ROS), and reactive nitrogen species (RNS) inhibition as well as cytotoxicity in HK-2, THP-1 monocytes, and SH-5YSY neuroblastoma cell lines were studied for the TE extract obtained under optimized conditions." (PMID 34869538, 2021).
colorectal cancer (9 papers, 2020 to 2025). A primary or metastatic malignant neoplasm that affects the colon or rectum. "It has been reported that low levels of BChE after colorectal cancer surgery increase the risk of surgical site infection." (PMID 39768948, 2024). "Recent studies have suggested that serum butyrylcholinesterase levels may serve as a novel biomarker associated with postoperative infectious complications and surgical site infection severity following colorectal cancer surgery." (PMID 41470232, 2025). "Reduced BCHE activity in blood plasma is associated with shorter survival times in pancreatic cancer patients, and it has been observed to have low expression levels in colorectal carcinoma while exhibiting high expression in oral cancer and ovarian cancer." (PMID 40751365, 2025). "Recent studies showed that butyrylcholinesterase plasma level has emerged as a potential predictive marker for the surgical complications that occurred after colorectal cancer resection." (PMID 38978990, 2024). "BCHE's low expression level has been documented in colorectal cancer, and its activities were found to be decreased in COAD patients." (PMID 35967794, 2022). "BCHE has been a very appealing biomarker in cancer diagnosis; for instance, it has low expression in colorectal carcinoma and high expression in ovarian cancer." (PMID 35915658, 2022). "Notably, high expression of BCHE has been reported in breast cancer, while minimal expression has been observed in colorectal cancer." (PMID 40107973, 2025). "BCHE may represent one such protein marker in some tumors such as breast cancer, colorectal carcinoma, oral squamous cell carcinoma, and lung squamous cell carcinoma." (PMID 35915658, 2022).